UHRF1 (ubiquitin like with PHD and ring finger domains 1)
Diseases named in the same sentence as UHRF1 in open-access papers (continued):
Sharing a sentence is not in itself a finding about the gene and the disease.
lung cancer (continued). "Similarly, in a study, lung cancer patients harboring KRAS mutant tumors with high UHRF1 expression had poorer prognosis." (PMID 39051184, 2024). "Similarly, in lung cancer, even at early stages, UHRF1 overexpression has significant implications for disease progression and treatment response." (PMID 39051184, 2024). "We hypothesize, that this broad effect across large number of TSGs is what contributes to the role of UHRF1 in lung cancer." (PMID 37407562, 2023). "This lung-cancer-specific TSG set was significantly enriched in UHRF1-depleted samples." (PMID 37407562, 2023). "Given the in vitro and in vivo data pointing to a role of UHRF1 in KRAS-driven lung cancer, we hypothesized that human lung cancer patients with elevated UHRF1 levels may have a worse prognosis than patients with low UHRF1 expression." (PMID 37407562, 2023). "Our observations suggest that in lung cancer UHRF1 may be a potential effector of KRAS that mediates its role in DNA methylation." (PMID 37407562, 2023). "We find that at least 80 lung cancer-specific TSGs are regulated by UHRF1." (PMID 37407562, 2023). "In vivo, UHRF1 knock-out inhibited tumor growth of KRAS-driven mouse lung cancer models." (PMID 37407562, 2023). "Finally, in lung cancer patients high UHRF1 expression is anti-correlated with TSG expression and predicts worse outcomes for patients with KRAS mutant tumors." (PMID 37407562, 2023). "Finally, from the subset of genes that were anticorrelated with both KRAS and UHRF1 expression we selected genes whose increased expression was protective (hazard ratio <1) in KRAS mutant lung cancer patients." (PMID 37407562, 2023). "Interestingly, the absence of WDR79 expression was accompanied with the loss of UHRF1 expression in MRC‐5 cells, whereas a positive correlation between WDR79 and UHRF1 was found in tested lung cancer cell lines." (PMID 29516630, 2018). "Consistent with RNA-seq data showing UHRF1 overexpression in lung cancers, the increased UHRF1 proteins could be clearly detected in 7 out of 10 tumor samples." (PMID 27462454, 2016). "Daskalos and his colleagues reported that UHRF1 is a prominent epigenetic switch that controls cell cycle in lung carcinoma due to its ability to smiantain the transcriptional silencing of tumor suppressor genes through sustaining their promoters in a hypermethylated condition." (PMID 27431502, 2016). "Combinations of UHRF1 and several other lung cancer biomarkers including ones originally identified by our group may yield a better outcome." (PMID 20517312, 2010). "Therefore, detection of UHRF1 expression in tissue specimens by immunohistochemistry can be useful for diagnosis of lung cancer in all pathological stages." (PMID 20517312, 2010). "The UHRF1 is overexpressed in various types of lung cancer from early pathological stage." (PMID 20517312, 2010). "Research by Kostyrko's team at the University of California, USA, has discovered that knocking out UHRF1 can inhibit the growth of KRAS-driven mouse lung cancer tumors, suggesting that UHRF1 may become a potential therapeutic intervention target for KRAS-driven cancers." (PMID 40083325, 2025). "Of note, UHRF1 was not included in the CRISPR DepMap libraries nor in the genome-wide CRISPR library used in our previous work, therefore we were unable to establish if complete knock-out of UHRF1 in 2D could be a dependency in KRAS mutant lung cancer cell lines." (PMID 37407562, 2023). "Nevertheless, it has been recently observed that miR-193a-3p repressed the metastasis of lung cancer cells by targeting several proteins highly expressed in NSCLC including UHRF1 indicating that miR-193a-3p negatively modulates the expression of UHRF1 in NSCLC." (PMID 27839516, 2016).
lung cancer (continued). "In conclusion, our data indicate that immunohistochemical staining of UHRF1 may ameliorate the sensitivity and specificity of current sputum examination for cancer detection, and/or to score the malignant potential of lung cancer using biopsy/resected tissue specimens accurately." (PMID 20517312, 2010). "Importantly, UHRF1 expression was observed in 50% of lung cancer cases in the early stage (T0+T1)." (PMID 20517312, 2010). "A study on SCLC, characterized by an aggressive course and a poor prognosis, showed that reducing UHRF1 levels increased the chemosensitivity of SCLC cells to cisplatin, a cornerstone in the combination chemotherapy regimen for this type of lung cancer." (PMID 39051184, 2024). "Another study on KRAS mutant lung adenocarcinoma identified UHRF1 as a critical target for cardiac glycosides, potent DSB repair inhibitors, in sensitizing KRAS mutant lung cancer to chemotherapy." (PMID 39051184, 2024). "Ubiquitin-like with PHD and ring finger domains 1 (UHRF1) is a chromatin modifier, which participates in DNA methylation and can contribute to cancer progression in many tumors, including lung cancer." (PMID 38317133, 2024). "ZNF304 is not highly expressed in lung tumors and its expression is significantly anti-correlated with UHRF1 expression in lung adenocarcinoma patients carrying a KRAS mutation, suggesting that UHRF1 may instead mediate this phenotype in KRAS-driven lung cancer." (PMID 37407562, 2023). "In line with this, here we show that genetic ablation of UHRF1 in combination with pharmacological inhibition of KRAS G12C, MEK, or PI3K results in a synergistically anti-proliferative effect in KRAS mutant lung cancer cells in vitro." (PMID 37407562, 2023). "To identify KRAS-specific vulnerabilities in lung cancer, we performed RNAi screens in primary spheroids derived from a Kras mutant mouse lung cancer model and discovered an epigenetic regulator Ubiquitin-like containing PHD and RING finger domains 1 (UHRF1)." (PMID 37407562, 2023). "Accumulating evidence suggests that ubiquitin‐like with plant homeodomain and ring finger domains 1 (UHRF1) is overexpressed in non‐small cell lung cancer (NSCLC); however, the expression and function of UHRF1 in the subtype of NSCLC are still unclear." (PMID 32495469, 2020). "To test if UHRF1 could be a direct effector of oncogenic KRAS in lung cancer, we depleted KRAS in lung cancer cell lines and quantified the levels of UHRF1 protein." (PMID 37407562, 2023). "In general, our results indicate that TSGs regulated by UHRF1 in lung cancer are non-overlapping with those proposed to be UHRF1-regulated in CRC, likely due to tissue-specific effects." (PMID 37407562, 2023). "This suggests that high expression of UHRF1 may drive TSG silencing and thus contribute to lung cancer progression." (PMID 37407562, 2023). "To further determine whether there was a correlation between WDR79 and UHRF1, we detected the expression of endogenous WDR79 and UHRF1 in human lung fibroblasts MRC‐5 and human lung cancer cell lines A549, H1299 and HTB182." (PMID 29516630, 2018). "In addition, an inverse correlation between UHRF1/2 overexpression and DNMT3A proteins is also observed in lung cancer cell lines." (PMID 27462454, 2016). "Recently, UHRF1's overpression has also been described in lung cancer cells, particularly in non-adenocarcinomas." (PMID 21496237, 2011). "The UHRF1 expression was observed in all histological types of lung cancer, especially in non-adenocarcinomas (non-ADCs), both in the US and Japanese cases." (PMID 20517312, 2010). "We observed overexpression of UHRF1 in lung cancer cases, especially in non-ADC cases, regardless of ethnic groups, indicating that frequent overexpression of UHRF1 in non-ADC is common worldwide." (PMID 20517312, 2010).
lung cancer (continued). "We also detected UHRF1 mRNA in Japanese cases by quantitative TaqMan PCR and found that UHRF1 mRNA was up-regulated in the overall lung cancers, especially in non-ADC, as the same as UHRF1 protein detected by immunohistochemistry." (PMID 20517312, 2010). "In line with observations from human KRAS mutant cell lines, Cre-mediated in vitro knock-out of Uhrf1 in UKP cells decreased colony growth in 2D and 3D compared to the empty adenovirus control, further supporting a critical role for UHRF1 in KRAS-driven lung cancer." (PMID 37407562, 2023). "Thus, despite increased DNMT3A transcripts in lung cancers, DNMT3A at the level of proteins is actually substantially reduced in lung tumors, most likely as a consequence of targeted degradation of DNMT3A by overexpressed UHRF1/2." (PMID 27462454, 2016). "Significantly, although RNA-seq data indicate increased DNMT3A transcripts in lung cancers, substantially reduced levels of DNMT3A proteins were actually detected in the tumors, and the levels of DNMT3A proteins exhibited a strong inverse correlation with that of the increased UHRF1 and UHRF2." (PMID 27462454, 2016). "In this report, we examined UHRF1 expression using 56 US and 322 Japanese lung cancer cases by immunohistochemical analysis and found that expression of UHRF1 was significantly up-regulated in almost all histological types of lung cancers, especially in non-ADCs." (PMID 20517312, 2010). "Interestingly, although expression of UHRF1 was detected in almost all histological types of the lung cancers, its expression was significantly higher in non-ADCs; 84% of non-ADCs showed high expression of UHRF1, whereas 32% of ADCs were overexpressed UHRF1 (P=9 × 10−5, χ2 test)." (PMID 20517312, 2010).
prostate carcinoma (27 papers, 2014 to 2026). A carcinoma that arises from epithelial cells of the prostate gland. "We have shown that UHRF1 is highly expressed in enzalutamide-resistant prostate cancer cells and its expression correlates with the loss of AR-dependent glandular features." (PMID 41760602, 2026). "Studies have indicated that exosomal biomarkers, TKTL1, and UHRF1 are associated with the prognosis of prostate cancer and hold potential as tumor markers." (PMID 37838928, 2024). "UHRF1 functions as an oncogene in prostate cancer and appears to be capable of predicting the risk of biochemical recurrence in PCa patients after radical prostatectomy, and may serve as a potential therapeutic target for PCa." (PMID 26884069, 2016). "Knocking down UHRF1 led to increased AR expression and enhanced the activity of canonical AR signaling pathway in prostate cancer cells." (PMID 41760602, 2026). "In this study, we demonstrated the critical role of the epigenetic regulator UHRF1 in the enzalutamide resistance development of prostate cancer." (PMID 41760602, 2026). "This epigenetic regulation mechanism implicates UHRF1 in the maintenance of gene expression patterns conducive to prostate cancer progression." (PMID 39051184, 2024). "AKT1 contributes to the resistance to enzalutamide (abiraterone) in prostate cancer (PCa) by modulating the phosphorylation of UHRF1." (PMID 38725075, 2024). "One study on prostate cancer showed that UHRF1 overexpression is characterized by its affinity for the promoter of silenced genes, where it modulates histone H3K9 methylation via the histone methyltransferase EZH2." (PMID 39051184, 2024). "Combination Therapies: The synergistic application of PARP and HDAC inhibitors has demonstrated enhanced efficacy in prostate cancer models, and this has been attributed to the depletion of UHRF1." (PMID 39051184, 2024). "It has been reported that the expression of UHRF1 steadily increased with the elevation of Gleason grade of prostate cancer (PCa)." (PMID 36593255, 2023). "UHRF1 as a key epigenetic regulator, plays a critical role in prostate cancer (PCa) development, and its expression is positively correlated with the degree of malignancy." (PMID 36593255, 2023). "Knockdown of UHRF1 in prostate cancer cells reduced their malignant characteristics, signifying its important role in prostate cancer progression." (PMID 29899856, 2018). "FOXM1 and UHRF1 are also consistently expressed in prostate cancer tumor specimens and cells, with high correlation between the two molecules." (PMID 29752436, 2018). "This study provided evidence that dihydroartemisinin can act as potential therapeutic agent in the treatment of prostate cancer, perhaps by influencing UHRF1 expression." (PMID 29899856, 2018). "Furthermore, inhibition of UHRF1 restored AR pathway activity and re-sensitized resistant prostate cancer cells to enzalutamide." (PMID 41760602, 2026). "Additional cancer-associated genes affected by promoter-associated risk alleles include CLIC1, which facilitates prostate cancer proliferation and migration; MICA, which enhances immune evasion mechanisms; and UHRF1 BP1, which supports prostate tumor progression through epigenetic regulation." (PMID 41468516, 2025). "Moreover, in DU145 prostate cancer cells UHRF1 promotes spindle assembly and chromosome congression in mitosis by catalyzing EG5 polyubiquitination." (PMID 38725075, 2024). "Under the same experimental conditions, we found that 2i treatment did not cause a significant reduction of UHRF1 or DNMT1 proteins in LNCaP (prostate cancer), Bel7402, C33A and SiHa (cervical cancer) cells." (PMID 30696879, 2019). "Furthermore, UHRF1 depletion significantly promoted sensitivity to docetaxel in a prostate cancer xenograft model." (PMID 29752436, 2018). "In addition, FOXM1 and UHRF1 are highly correlated in tumor specimens and prostate cancer cell lines." (PMID 29752436, 2018).
prostate carcinoma (continued). "The finding raised the possibility that the differentially expressed UHRF1 might contribute to the progression of prostate cancer." (PMID 26884069, 2016). "Therefore, our findings elucidate an intracellular molecular mechanism that promotes prostate cancer lineage plasticity and suggest that UHRF1 may serve as a potential therapeutic target for overcoming resistance to AR-targeted therapies." (PMID 41760602, 2026). "In prostate cancer models, DHA significantly downregulates expression of UHRF1 (Ubiquitin-like protein) and DNMT1." (PMID 40697663, 2025). "In prostate cancer, FOXM1 has been reported to regulate cancer stem cells (CSCs) through regulating UHRF1 gene expression and related taxane resistance." (PMID 32629770, 2020). "Expression of UHRF1 correlates negatively with multiple tumor suppressors and positively with EZH2 expression (histone methyltransferase) in tumors and prostate cancer cell lines." (PMID 29899856, 2018). "Overexpression of UHRF1 accompanied with downregulation of tumor suppressor genes and increased expression of EZH2 (H3K27 methyltransferase) in prostate cancer cells contributed to the poor clinical prognosis and lethal progression disease." (PMID 28881702, 2017). "Overexpression of both UHRF1 and EZH2 coordinately suppressed antitumor genes and contributed to prostate cancer pathogenesis and metastasis." (PMID 27487138, 2016). "Thus, UHRF1 along with the SUV39H1 histone methyltransferase, and DNA methyltransferases are thought to be involved in the epigenetic silencing of genes in prostate cancer." (PMID 29899856, 2018). "FOXM1 or UHRF1 expression levels showed high correlation in prostate cancer cells and non-malignant prostate epithelial cells." (PMID 29752436, 2018). "Additionally, we assessed the expression of FOXM1 and UHRF1 proteins in a panel of prostate cancer cell lines and non-malignant prostate epithelial cells." (PMID 29752436, 2018). "Notably, the auxiliary protein Uhrf1 found in the ‘darkorange’ module has previously been shown to interact with PRC2 members Ezh2 and Suz12 in prostate cancer cells, where elevated UHRF1 levels correlate positively with an increase in EZH2 and were associated with poor clinical outcome." (PMID 25605797, 2015).
colon cancer (22 papers, 2015 to 2024). "Ubiquitin-like with PHD and RING finger domains 1 (UHRF1) is upregulated in colon cancer cells and associated with silencing tumor suppressor genes (TSGs) to promote colon cancer cell proliferation." (PMID 35951156, 2022). "The authors observed a significantly increased UHRF1 expression at both transcriptomic and proteomic levels in colon cancer tissues and found positive association of this overexpression with metastasis, poor clinical staging and p16 silencing." (PMID 28881702, 2017). "Since we found UHRF1 4KR effect on colon cancer cell proliferation, we tested whether UHRF1 acetylation-deficient form could alter expression level of these TSGs by RT-qPCR." (PMID 35951156, 2022). "Furthermore, upregulated JDP2 expression by acetylation-deficient mutant of UHRF1 might be an important epigenetic target for colon cancer cell proliferation." (PMID 35951156, 2022). "In colon cancer, UHRF1 histone- and hemimethylated DNA binding functions epigenetically suppressed the levels of tumor suppressor genes (TSGs) and governed the maintenance of DNA methylation patterns." (PMID 39709438, 2024). "Hinokitiol, a tropolone-related natural compound with antitumor activity, has been recently demonstrated to induce DNA demethylation via UHRF1 inhibition in colon cancer cells." (PMID 37380646, 2023). "The acetylation-deficient mutant UHRF1 4 KR loses the ability to inhibit JDP2 and the latter gene will be upregulated to suppress colon cancer cell proliferation." (PMID 37701039, 2023). "Studies suggest that UHRF1 is upregulated in different cancer cells, another study determined the oncogenic propriety of UHRF1 on colon cancer cell proliferation." (PMID 35951156, 2022). "JDP2 gene is known as one of UHRF1 target genes that correlates with increased UHRF1 expression and promoter DNA methylation in colon cancer cells and also known for inhibiting cancer cell proliferation by repressing cell cycle progression." (PMID 35951156, 2022). "β-Thujaplicin reduced proliferation in MCF7 cells, suppressed cancer stemness in glioma U87MG, induced cell cycle arrest, apoptosis, and DNA methylation via DNMT1 and UHRF1 in colon cancer, and restricted liver cancer growth by apoptosis and cell cycle arrest." (PMID 36697960, 2022). "Recent study indicates that UHRF1 acts as an oncogene by silencing 8 selected TSGs in colon cancer cells through promoter hypermethylation of these TSGs and correlated with poor prognosis and the shortened overall survival rates." (PMID 35951156, 2022). "Recent genetic studies suggest that inhibition of the UHRF1 SRA–DNA interaction is a strategy for inhibiting tumor suppressor gene silencing in colon cancer cells." (PMID 31481468, 2019). "A functional UHRF1 SRA domain, as evaluated by point mutations that disrupt DNA interaction, is required for sustaining the oncogenic activity of UHRF1 in colon cancer cells, adding to the motivation of UHRF1 SRA antagonism as a cancer therapeutic strategy." (PMID 31481468, 2019). "Therefore, UHRF1 acetylation is required for DNA methylation maintenance in colon cancer cells by binding to the hemi-methylated DNA." (PMID 38725075, 2024). "Additionally, we reanalysed a publicly-available dataset where UHRF1 was depleted in HCT116 colon cancer cells using adenovirus-mediated transfection of shRNA and where only a limited analysis of ISG by RT-qPCR had been reported." (PMID 37246786, 2023). "JDP2 is a transcription repressor and is repressed by UHRF1 in colon cancer." (PMID 37701039, 2023). "Similarly, UHRF1 is necessary for colon cancer survival, and this is likely to depend on its DNA methylation-promoting function." (PMID 35625988, 2022).